VWF (von Willebrand factor)
Diseases named in the same sentence as VWF in open-access papers (continued):
Sharing a sentence is not in itself a finding about the gene and the disease.
cerebrovascular disease (7 papers, 2014 to 2025). "This study shows that VWF serum levels are significantly increased in both acute and chronic cerebrovascular disorders compared with healthy persons." (PMID 24937073, 2014). "In addition to being chronically elevated in patients with cerebrovascular disease, the plasma level of vWF is known to increase in acute ischemic stroke." (PMID 28570705, 2017). "However, larger prospective studies and standardized test systems are further needed before determining whether levels of VWF and ADAMTS13 can be used as a clinical marker to predict the risk of cardiovascular/cerebrovascular diseases in individual patients." (PMID 31379722, 2019).
HELLP syndrome (7 papers, 2018 to 2025). A life-threatening condition that can potentially complicate pregnancy. "In the same study, PE and HELLP syndrome were correlated with increased values of VWF: Ag with a statistically significant difference between HELLP syndrome and normal pregnancy (p < 0.05)." (PMID 35409211, 2022). "Active multimeric von Willebrand factor (VWF) serum level is higher in HELLP syndrome compared to normal pregnancy." (PMID 35208649, 2022). "Second, plasma VWF antigens and their adhesive activities are both significantly elevated in patients with PE and those with HELLP syndrome." (PMID 33212799, 2020). "Third, plasma ADAMTS-13 antigens and activity are reduced in patients with PE or HELLP syndrome, resulting in a kinetic ADAMTS-13 deficiency and hyperadhesive VWF." (PMID 33212799, 2020). "Damage to vascular endothelial cells produced by antiangiogenic factors, exposure to TNFα, and high levels of active VWF seen in HELLP syndrome may interact and result in thrombotic microangiopathy." (PMID 35208649, 2022).
hemangioma (7 papers, 2005 to 2025). A benign vascular lesion characterized by the formation of capillary-sized or cavernous vascular channels. "This panel approach is necessary because vWF, being a specific marker for endothelial differentiation, is also expressed in other vascular lesions, including hemangiomas." (PMID 40666093, 2025).
hypertrophic obstructive cardiomyopathy (7 papers, 2020 to 2026). "This phenomenon reflects an increased risk of bleeding from VWF dysfunction in similar high-shear stress states, such as hypertrophic obstructive cardiomyopathy, ventricular septal defects, and para-valvular leaks." (PMID 36449459, 2022). "The deficiency of HMWM of vWF in valvular heart disease and obstructive hypertrophic cardiomyopathy manifests with gastrointestinal, skin or mucosal bleeding." (PMID 33096906, 2020). "Shear stress-induced degradation of VWF is also observed in other cardiac conditions, including left ventricular assist devices, hypertrophic cardiomyopathy, and mitral and aortic regurgitation." (PMID 39456826, 2024). "In another study of 28 patients with obstructive hypertrophic cardiomyopathy, plasma levels of vWF were normal in all patients." (PMID 33096906, 2020).
myeloproliferative neoplasm (7 papers, 2013 to 2025). A clonal hematopoietic stem cell disorder, characterized by proliferation in the bone marrow of one or more of the myeloid (i.e., granulocytic, erythroid, megakaryocytic, and mast cell) lineages. "Myeloproliferative disorders can paradoxically increase bleeding risk due to heightened platelet counts, which can cause increased shear stress and proteolysis of VWF." (PMID 39456826, 2024). "Acquired vWF deficiency is associated with CML and other myeloproliferative disorders." (PMID 24367730, 2013). "In addition, the liver parenchyma of a non-Z-patient with chronic myeloproliferative disease (PiMM-genotype) was analyzed using ATZ11, anti-AAT, and anti-VWF antibodies." (PMID 24646657, 2014).
peripheral artery disease (7 papers, 2014 to 2024). "We found significantly higher vWF and Ristocetin cofactor activity in patients with peripheral artery disease." (PMID 36769870, 2023). "We assumed a large multimer index of <80% as loss of VWF large multimers since 59.0% of patients with severe AS had the indices of <80%, while no control patients or patients with peripheral artery disease, except for 2 patients, exhibited the indices of <80%." (PMID 38268521, 2024).
pulmonary fibrosis (7 papers, 2016 to 2024). Chronic progressive interstitial lung disorder characterized by the replacement of the lung tissue by connective tissue, leading to progressive dyspnea, respiratory failure, or right heart failure. "Interestingly, decreased VWF was associated with decreased pulmonary fibrosis and increased bone marrow hematopoiesis." (PMID 30978983, 2019). "NAC promoted immune response and suppressed epithelial-mesenchymal transformation (EMT) to relieve COPD-induced pulmonary fibrosis in vitro and in vivo by inhibiting the VWF/p38 MAPK axis." (PMID 34479474, 2021). "Apart from melanocytes, AP3B1 defects include prolonged bleeding due to the disrupted transport of the von Willebrand factor (VWF) in Weibel–Palade bodies (WPBs), immunodeficiency, and pulmonary fibrosis due to defects in lamellar body biogenesis in type II pneumocytes." (PMID 39339853, 2024). "At last, whether NAC can alleviate COPD-induced pulmonary fibrosis by inhibiting the VWF/p38 MAPK axis was investigated." (PMID 34479474, 2021). "Furthermore, the obtained data suggested that NAC inhibited p38 MAPK phosphorylation by reducing the VWF expression to inhibit the pulmonary fibrosis in COPD." (PMID 34479474, 2021). "Hence, we hypothesized that the transfer of NAC might relieve pulmonary fibrosis in COPD by regulating the VWF/p38 MAPK axis." (PMID 34479474, 2021). "Thus, the inhibition of VWF level has the potential to attenuate the pulmonary fibrosis in COPD." (PMID 34479474, 2021). "In addition, the data in the present study also confirmed that VWF expression increased in COPD, and NAC could reduce the VWF expression to relieve pulmonary fibrosis in COPD." (PMID 34479474, 2021). "On the other hand, the levels of von Willebrand factor, PAI-1, and matrix metalloproteinase 12 were elevated in lung endothelial cells isolated from a murine bleomycin-induced pulmonary fibrosis model." (PMID 39337840, 2024). "Studies have reported that NAC can improve COPD-related pulmonary fibrosis by activating immune response and suppressing the EMT process through VWF/P38 MAPK signaling pathway in vivo and in vitro experiments." (PMID 36045410, 2022). "Due to the limited known researches, the roles of NAC, VWF, and p38 MAPK as well as their interaction in the pulmonary fibrosis in the progression of COPD should be more clearly investigated." (PMID 34479474, 2021). "However, the mechanism by which NAC-mediated VWF/p38 MAPK affects pulmonary fibrosis in COPD involving the immune response and EMT is still poorly understood, highlighting a major gap in knowledge given that NAC-mediated VWF/p38 MAPK may be of significance to pulmonary fibrosis in COPD." (PMID 34479474, 2021). "NAC could ameliorate COPD-induced pulmonary fibrosis by promoting immune response and inhibiting the EMT process via the VWF/p38 MAPK axis." (PMID 36045410, 2022). "Returning to the hypothesis in the beginning, we provided evidence in our study that NAC exerted inhibited properties in pulmonary fibrosis in COPD by promoting immune response and suppressing ETM through the downregulation of VWF/p38 MAPK axis." (PMID 34479474, 2021). "Collectively, NAC could ameliorate COPD-induced pulmonary fibrosis by promoting immune response and inhibiting EMT process via the VWF/p38 MAPK axis, therefore providing us with a potential therapeutic target for treating COPD." (PMID 34479474, 2021).
ST Elevation Myocardial Infarction (7 papers, 2013 to 2025). A myocardial infarction that produces elevation in the ST segments of the ECG. "The pronounced vWF elevation in ACS was further supported by a large-scale study in ST-elevation myocardial infarction (STEMI) patients, where vWF concentrations were 1.5 times higher compared to controls, reinforcing its role in plaque rupture and thrombosis." (PMID 41007843, 2025). "VWF is also an independent risk factor for first STEMI: levels of VWF are significantly increased in patients with first ST-elevation myocardial infarction (STEMI) rather than in controls." (PMID 28634421, 2017). "The ARMADA study evaluated anti-inflammatory effects of heparin and enoxaparin in Non-ST-Elevated Myocardial Infarction (Non-STEMI) and reported that inflammatory markers (CRP and von Willebrand factor) are affected more by LMWH compared to UFH." (PMID 26064103, 2015).
acquired thrombotic thrombocytopenic purpura (6 papers, 2019 to 2025). Acquired thrombotic thrombocytopenic purpura is the non-hereditary form of thrombotic thrombocytopenic purpura (TTP), characterized by profound peripheral thrombocytopenia, microangiopathic hemolytic anemia (MAHA) and single or multiple organ failure of variable severity. "The second is a bivalent nanobody, caplacizumab, which is a tandemly repeated VHH for the anti-von Willebrand factor (vWF) linked via a trialanine linker that has been approved for the treatment of acquired thrombotic thrombocytopenic purpura (aTTP)." (PMID 37208691, 2023). "Caplacizumab, an anti-vWF bivalent single-domain nanobody, inhibits vWF–platelet interaction and is already used to treat acquired thrombotic thrombocytopenic purpura." (PMID 35746657, 2022). "In addition to Ozoralizumab, other therapies for cancer treatment, such as caplacizumab, a nanobody targeting von Willebrand factor (VWF), have been investigated for their efficacy in treating acquired thrombotic thrombocytopenic purpura (aTTP)." (PMID 41301547, 2025). "Interestingly, in August 2018, Caplacizumab, a Nb directed against von Willebrand Factor (vWF), was EMA-approved for acquired thrombotic thrombocytopenic purpura (aTTP)." (PMID 31544811, 2019).
brain tumor (6 papers, 2007 to 2025). "This is in agreement with earlier findings that also highlight the theranostic value of VWF in brain tumor patients." (PMID 34815502, 2021). "Further validation of 110 potential noninvasive biomarkers yields three biomarker panels comprising a total of 19 biomarkers (including DES, VWF, and COL1A1) for accurate discrimination of two types of brain tumors and normal controls." (PMID 39716938, 2025). "More importantly, the tumor capillaries showed co-localization of KCa channels and vWF in tumor area of CRL-5904 tumor and in human metastatic brain tumor tissue." (PMID 17359538, 2007).
carotid atherosclerosis (6 papers, 2014 to 2022). A thickening and loss of elasticity of the walls of carotid arteries that occur with formation of atherosclerotic plaques. "The elevated VWF level was associated with the endothelial disfunction and higher cardiovascular risk in individuals with subclinical carotid atherosclerosis." (PMID 35935662, 2022). "Similarly, we confirmed a target concentration-dependent inhibition of VWF in samples from patients with carotid atherosclerosis." (PMID 32636459, 2020).
cerebral small vessel disease (6 papers, 2013 to 2022). Cerebral small vessel disease is the term currently used to pathological processes that affect the brain parenchymal circulation (arterioles, capillaries, and veins). "VWF has been associated with markers of cerebral small-vessel disease that are known risk factors for dementia, including white matter hyperintensities on MRI and microhaemorrhages co-localised with beta-amyloid deposits." (PMID 29615758, 2018). "We present evidence that vWF breaches the endothelium and is expressed in a transmural distribution pattern in cerebral small vessel disease (SVD)." (PMID 24086636, 2013). "As von Willebrand factor may promote cerebral endothelial integrity, insufficient von Willebrand factor is consistent with dysfunctional cerebral endothelium and increased basal ganglia perivascular spaces in cerebral small vessel disease." (PMID 27576214, 2016). "A recent systematic review analyzed the role of vascular (e.g. VWF, homocysteine) and systemic (e.g. CRP, IL-6) inflammatory biomarkers in relation to cerebral small vessel disease (SVD) in a non-CKD population." (PMID 35042473, 2022).
colon carcinoma (6 papers, 2014 to 2022). "VWF incorporated into a panel with several other protein and glycomic plasma markers showed promising results in the early detection of colon cancer, with high VWF levels correlating with cancer risk." (PMID 35327035, 2022). "In our article, VWF was low expressed in colon cancer tissue and was a high-risk gene." (PMID 35991564, 2022). "And this conclusion was further confirmed by the finds that vWF inhibition effectively decreased tumor metastasis in murine and reduced the adhesion of colon cancer cells to endothelial cells (ECs)." (PMID 30279208, 2018). "In a previous study of colon carcinoma specimens, almost all (5/6) were found to possess higher vWF mRNA levels than their patient-matched normal tissues." (PMID 25886574, 2015). "Additionally, studies have reported that plasma vWF was significantly increased in patients with colon cancer, ovarian cancer, and gastric adenocarcinoma." (PMID 30279208, 2018). "It was because VWF could promote a highly aggressive nature of colon cancer." (PMID 35991564, 2022). "ALPL, APOL6, SON, VWF, FITM2, and ZEB1-AS1 were significantly differentially expressed in normal and colon cancer tissues." (PMID 35991564, 2022). "Both VWF and ADAMTS13 have been explored as potential biomarkers of cancer to aid in the early detection of colon cancer and HCC." (PMID 35327035, 2022).
diabetic nephropathy (6 papers, 2016 to 2025). "Elevated plasma levels of VWF were associated with diabetic nephropathy in the present study, which was also verified by other authors." (PMID 26770985, 2016). "Elevated levels of VWF can promote microthrombi formation in vasculature, leading to hypercoagulability status and formation of D-Dimer, which is a fragment of fibrin degradation and has also been associated with diabetic nephropathy." (PMID 26770985, 2016). "The deterioration of renal function in diabetic nephropathy is associated with even lower ADAMTS-13 levels and a high VWF/ADAMTS-13 ratio." (PMID 40390002, 2025). "Additionally, plasma ADAMTS-13 levels are decreased in diabetic nephropathy, potentially due to peripheral consumption for the cleavage of chronically increased VWF and an increase in circulating proteolytic enzymes (thrombin and plasmin) that cleave ADAMTS-13." (PMID 40390002, 2025).
factor XI deficiency (6 papers, 2015 to 2025). A coagulation disorder characterized by the partial or complete absence of factor XI activity in the blood. "Laboratory findings demonstrating prolonged aPTT and severe factor XI deficiency with preserved platelet count, vWF and FVIII within acceptable ranges." (PMID 41458817, 2025).
falciparum malaria (6 papers, 2011 to 2020). "The strong correlation between IL-27 and vWF as a marker of endothelial cell activation also support a link between endothelial cells and IL-27 in vivo during falciparum malaria, either as a cellular source, cellular target or both." (PMID 31964363, 2020). "In contrast, peripheral parasitemia correlated with endothelial activation (Ang-2, VWF and E-selectin) in both vivax and falciparum malaria, and with total biomass (HRP2) in falciparum malaria." (PMID 25569250, 2015). "Further studies confirmed release of VWF after endothelial cell activation in patients with falciparum malaria and detected adhesion of PRBCs to platelet-decorated ultra-large VWF (ULVWF) strings." (PMID 22168261, 2011). "Increased von Willebrand Factor (vWF) and decreased levels of the vWF cleaving protease, ADAMTS 13, have recently been described in uncomplicated vivax malaria and severe falciparum malaria, and could contribute to microvascular obstruction." (PMID 21666785, 2011).
fibrosis (6 papers, 2016 to 2025). the formation of excess fibrous connective tissue in an organ or tissue in a reparative or reactive process. "Signals for both C1q and vWF were significantly lower in areas with fibrotic lesions and CCs when compared to atheroma areas (C1q: atheroma vs CC p<0.01, atheroma vs fibrosis p<0.001; vWF atheroma vs CC p<0.001, atheroma vs fibrosis p<0.05)." (PMID 38155969, 2023). "Analyses on hepatic angiogenesis in NAFLD patients are limited in number if compared to those in animal model studies; however, the liver of patients with NAFLD showed increased expression of the endothelial marker von Willebrand factor (vWF), especially in those subjects with advanced fibrosis." (PMID 34681219, 2021). "Moreover, offspring of HFD dams had altered methylation patterns in DMRs of genes that play important roles in hepatic fibrosis and lipid accumulation, including Ppargc1β, Fgf21, Ephb2 and VWF." (PMID 28414763, 2017).
hematoma (6 papers, 2015 to 2023). A hematoma is a collection of blood from a vascular structure into an extravascular space. "Following ICH, lactate accumulated around the hematoma; the numbers of PCNA+/vWF+ nuclei and PCNA+/DCX+ cells were significantly increased compared with the numbers in the Sham group." (PMID 29980670, 2018). "No hematoma was found in the sham group, and there was no positive expression of vWF in the sham group." (PMID 32328124, 2020).
Hypercholesterolemia (6 papers, 2009 to 2025). An increased concentration of cholesterol in the blood. "In spite of the presence of hypercholesterolemia, L-arginine preserved endothelium from adverse effects of risk factor as substantiated by significantly lower vWF in this group." (PMID 19309530, 2009). "In this mouse study, we have shown that siRNA-mediated robust silencing of plasma and endothelial VWF levels is also feasible in a setting of hypercholesterolemia and a diseased atherothrombosis-prone vasculature." (PMID 40093962, 2025). "APOE∗3-Leiden.CETP mice exhibited elevated plasma VWF levels compared with WT mice, alongside hypercholesterolemia and aortic atherosclerosis." (PMID 40093962, 2025). "Treatment with simvastatin in patients with impaired glucose tolerance and hypercholesterolemia reduced plasma levels of fibrinogen, FX:C, vWF:Ag, PAI-1, and FVII activity." (PMID 34176487, 2021). "The results showed that hypercholesterolemia induced significant endothelial injury characterized by increased vWF release within 4 weeks after initiation of a 1% cholesterol diet in LP group." (PMID 19309530, 2009). "The plasma levels of lipids were increased significantly in both groups of LP and EP after phase I. The hypercholesterolemia induced significant increased vWF release in LP group." (PMID 19309530, 2009). "However, studies have indicated that high oxidative stress, which occurs in hypercholesterolemia and MI, can impair ADAMTS13 activity and removal of VWF from the endothelial surface, providing an explanation for the effects of additional enzyme." (PMID 38693516, 2024).
Immunodeficiency (6 papers, 2021 to 2024). Failure of the immune system to protect the body adequately from infection, due to the absence or insufficiency of some component process or substance. "Rarely, Helicobacter pylori-diagnostics (1.8%), immunodeficiency diagnostics (2.8%), and von Willebrand factor, type 2B diagnostics (5.5%) were performed." (PMID 34486084, 2021).